IL22 (interleukin 22)
Diseases named in the same sentence as IL22 in open-access papers (continued):
Sharing a sentence is not in itself a finding about the gene and the disease.
hepatocellular carcinoma (continued). "In the course of this study, hepatocellular carcinoma was diagnosed in two patients with detectable IL-22." (PMID 22967278, 2012). "The activity of MAP kinases such as ERK and p38 after IL-22 stimulation in this study, is partly reminiscent of that in hepatoma cells observed in other studies." (PMID 22922995, 2012). "The growth of HepG2 human hepatocellular carcinoma cells was promoted by IL-22 through the activation of STAT3, ERK1/2 and the induction of antiapoptotic proteins." (PMID 21625390, 2011). "Similarly, elevated levels of IL-22 can also be detected in human cancers, including hepatocellular carcinoma and gastric cancer as well as non-small cell lung cancer." (PMID 35967401, 2022). "In HCC, metformin could regulate the Hippo signaling pathway to reduce interleukin-22-induced hepatocellular carcinoma." (PMID 36385965, 2022). "Also, IL-22 upregulates the production of acute-phase proteins in hepatoma cells, suggesting that it is involved in the regulation of inflammatory responses." (PMID 35054942, 2022). "Moreover, it has been shown that IL-22 promotes human hepatocellular carcinoma via activation of STAT3." (PMID 34941188, 2021). "Finally, N‐lys derived from hepatoma cells supported inflammatory splenic Th17 and Th1 polarization as detected by IL‐17, IL‐22 or interferon‐γ production." (PMID 32697038, 2020). "Regarding the role of TH22/IL-22 in cancers, evidence from early studies revealed that IL-22 promotes the growth of tumor cells in many types of cancers, including lung adenocarcinoma and hepatocellular carcinoma." (PMID 31637216, 2019). "IL-22 protein levels in serum of patients with HBV- and HCV-associated hepatocellular carcinomas is an indicator of poor prognosis, implying that virus-induced IL-22 may promote tumor development associated with these infections." (PMID 27303405, 2016). "Beside these well characterized immunopathological functions on epithelial tissues, the role of IL-22 in cancer cell biology has been recently reported in lung, gastric, colorectal, pancreatic, and hepatocellular carcinomas, whose cells expressed the IL-22R1/IL-10R2 receptor subunits." (PMID 25793261, 2015). "In hepatocellular carcinoma, IL-22 induces cell survival and proliferation." (PMID 25793261, 2015). "The underlying mechanisms may be explained by in vitro studies of HepG2 hepatocellular carcinoma cells that demonstrated an IL-22-mediated induction of various anti-apoptotic and mitogenic proteins." (PMID 23372820, 2013). "In viral hepatitis, IL-22 facilitates hepatocyte survival according to observations in humans and IL-22 transgenic mice, and anti-apoptotic actions are proposed as an explanation for its upregulation in patients with hepatocellular carcinoma." (PMID 23372820, 2013). "Likely by promoting hepatocyte survival, several studies indicate a protective role for IL-22 in experimental hepatitis and liver injury, a property that may on the other hand promote progression to hepatocellular carcinoma." (PMID 22967278, 2012). "An enhanced IL-22 expression has also been noted in tumor-infiltrating lymphocytes collected from hepatocellular carcinoma (HCC) patients." (PMID 28050571, 2016). "Previous work has shown that IL-22 up-regulates CD155 via the STAT3 pathway, thereby reducing sorafenib sensitivity in hepatocellular carcinoma cells and impairing NK-cell-mediated tumor cell lysis." (PMID 41562076, 2025). "Remarkably, miR-197 reduces STAT3 signaling via miR-197/IL-22/STAT3 and miR-197/IL-6/STAT3 pathways in human keratinocytes and hepatocellular carcinomas." (PMID 29890998, 2018). "IL-22 plays important roles in various human and animal liver diseases, such as acute liver injury, viral hepatitis, liver fibrosis, hepatocellular carcinoma (HCC), and alcoholic liver disease." (PMID 30515423, 2018).
hepatocellular carcinoma (continued). "A potent synergism between the IFN signaling system and IL-22 concerning activation of STAT1 was identified in human colon carcinoma cells, HepG2 hepatoma cells, and primary keratinocytes on a biochemical level." (PMID 27199988, 2016). "The effect of IFN-λ or IL-22 on HBV replication and cell viability was assessed in hepatoma cells expressing IL-10RB K47 or E47." (PMID 23519428, 2013). "In a rat hepatoma cell line, IL-22 was found to activate JAK1 but not JAK2, and STAT and the three major MAPK pathways." (PMID 40806452, 2025). "Moreover, it decreases the production of IL-22 by TH17 and TH1 cells in a murine hepatocellular carcinoma (HCC) tumor model in a dose-dependent manner." (PMID 37686159, 2023). "Hence, the effect of this SNP on cellular responsiveness to IFN-λ and IL-22 capable of suppressing HBV replication and increasing hepatoma cell viability was examined." (PMID 23519428, 2013). "Additionally, IL-22-positive cells are found in HCV patients in both peripheral blood and liver tissue as well as in patients with hepatocellular carcinoma." (PMID 23372820, 2013). "IL-10RB K47E was associated with the transcript level of IL-10RB in transformed B cells but not with the responses in hepatoma cells to IFN-λ or IL-22." (PMID 23519428, 2013). "We showed the protective activity of IL-22 and IFN-λ on chemotherapy-induced hepatoma cell death." (PMID 23519428, 2013). "Thus, IL-22 does not act on endothelial cells to promote hepatocellular cancer." (PMID 36551508, 2022). "Moreover, another prior study has indicated that IL-22 was upregulated in human Edmondson Grade III-IV hepatocellular carcinoma (HCC) and that IL-22R1 was highly expressed in aggressive HCC cases." (PMID 31935914, 2020). "Notably, the benefit of focused short-term application of IL-11 or IL-22 in acute disorders, such as APAP-induced ALI, should likely outweigh the inherent danger of these cytokines to promote in the long run tumor growth, which has been detected for IL-22 and hepatocellular carcinoma patients." (PMID 27199988, 2016).
liver disease (44 papers, 2011 to 2025). "The extensive range of AUD and alcohol associated liver disease investigated in this study showed that IL-22 levels correlated positively with markers of liver injury." (PMID 38162671, 2023). "Another group studied IL-22 levels in alcohol associated liver disease and found that they correlated with MELD." (PMID 38162671, 2023). "Ethanol-induced liver disease is typically associated with impairment of ILC3s in the gut from properly producing IL-22, thus fueling bacterial translocation." (PMID 33390852, 2021). "Elevated levels of IL-22 were associated with ascites (P = 0.006), hepatorenal syndrome (P < 0.0001), and spontaneous bacterial peritonitis (P = 0.001)." (PMID 22967278, 2012). "In this comprehensive review, we will summarize past and current findings regarding the roles of IL-22 and IL-22BP in liver diseases with a particular focus on the leading causes of advanced liver failure, namely, liver infections, liver damage, and liver malignancies." (PMID 33851257, 2021). "Secondly, therapeutic regimes could take advantage of an IL-22 blocking antibody in liver diseases in which IL-22 was shown to exhibit pathogenic effects, such as HCC." (PMID 33851257, 2021). "Additionally, a phase II-b trial of IL-22 reveals that IL-22 is free from important side effects and associated with a high rate of improvement in liver disease, highlighting its promising therapeutic opportunities 48-49." (PMID 32483425, 2020). "Moreover, IL-22 promotion of liver regeneration in mice with liver disease (caused by ConA) after PHx has been confirmed." (PMID 30515423, 2018). "Furthermore, elevated IL-22 levels were associated with liver-related complications, such as ascites, hepatorenal syndrome and spontaneous bacterial peritonitis." (PMID 22967278, 2012). "ILC3s secrete IL22, which seems to be crucial for host defense as the administration of IL22producing bacteria or IL22 itself reduces ethanol-induced liver disease in mice." (PMID 40151622, 2025). "The demonstrated hepatoprotective effects of IL-22 in liver diseases suggest that its homologous cytokine IL-24 also possesses therapeutic potential." (PMID 41288708, 2025). "In line with the anti-fibrotic function of IL-22, patients with Schistosoma japonicum infection had elevated hepatic IL-22 and decreased IL-22BP transcripts, correlating with reduced fibrosis and portal hypertension." (PMID 39156888, 2024). "We will focus on the type 3 cytokines IL-17A and IL-22, their roles during the different stages of liver disease in general and MASLD in particular and their therapeutic potential." (PMID 39156888, 2024). "In conclusion, the liver conservation function and liver regeneration promotion of IL-22 indicate the therapeutic potential of IL-22 in the treatment of human liver diseases." (PMID 37420298, 2023). "A short-term clinical trial of IL-22 reported improved Lille scores and a model for end-stage liver disease scores, implying the severity of liver disease, in patients with AH." (PMID 36611816, 2022). "IL-22 has a protective effect on liver injury and hepatitis diseases, and its safety and efficacy in the treatment of hepatitis have also been proved in human clinical experiments." (PMID 35592531, 2022). "In animal models of concanavalin-induced hepatitis or alcoholic hepatitis, the application of IL-22 can reduce the severity of liver disease." (PMID 36117587, 2022). "Indole metabolites produced by intestinal bacteria are known to control liver disease manifestation through a variety of mechanisms in addition to AhR activation and IL-22 production." (PMID 34209524, 2021). "These tissue protective and regenerative functions of IL-22 together suggest the therapeutic potential of this cytokine for the treatment of liver diseases." (PMID 34944732, 2021).
liver disease (continued). "Because the role of sexes in hepatic diseases is a pressing understudied topic, sex-dependent production of pro-regenerative IL-22 was analyzed herein in murine APAP-induced ALI and cell culture models of IL-22 expression." (PMID 34638962, 2021). "We aim to update what is known about IL-17A, IL-22, and retinoic acid in the pathobiology of liver diseases." (PMID 34211477, 2021). "To summarize, liver disease often leads to a shift in the commensal microbiome, inducing decreased levels of IL-22." (PMID 33851257, 2021). "Due to the mainly protective functions in other inflammatory liver diseases, a spotlight was cast once more on the effect of IL-22 in this particular liver pathology." (PMID 33851257, 2021). "The proportion of hepatic ILC3 is rare, but it has been shown to be involved in protection and pathogenesis via secretion of cytokines (such as IL-22 and IL-17) in several liver diseases." (PMID 33790913, 2021). "Previous studies indicate that IL-17 mediates liver disease progression by inducing inflammatory tissue responses, while IL-22 is hepatoprotective during liver injury." (PMID 34944732, 2021). "In conclusion, the hepatoprotective functions and liver regeneration promoting effect of IL-22 suggests the therapeutic potential of IL-22 in the treatment of human hepatic diseases." (PMID 32760208, 2020). "These facts indicate that IL-22 will be a potential new target for the treatment of liver disease in the future." (PMID 32760208, 2020). "Despite growing evidence suggests that IL-22 is a promising antidote to treat various hepatic disorders, the molecular basis of the liver protective activities of IL-22 needs to be fully characterized." (PMID 32483425, 2020). "As an emerging CD4+Th cytokine, IL-22 plays an overwhelming hepatoprotective and regenerative roles in various liver diseases with the activation of STAT3 pathway." (PMID 32760208, 2020). "In conclusion, IL-22 is a significant cytokine product of Th17 and serves an essential function in inflammatory and liver diseases." (PMID 31749919, 2019). "In conclusion, IL-22-FP has great potential for treatment of patients with liver disease that have undergone PHx." (PMID 30515423, 2018). "The hepatoprotective effects of IL-22 in various animal and human liver diseases have been investigated." (PMID 30515423, 2018). "Hepatic ILC3s were shown to be involved in protection or pathogenesis via secretion of cytokines (e.g., IL-22 and IL-17) in some liver diseases, although the percentage of hepatic ILC3s is rare." (PMID 28659927, 2017). "IL-22 has been previously reported to be protective against acute hepatitis as well as being known to induce regenerative response in hepatic disease models but it was reported to worsen inflammation in HBV-infected mouse model." (PMID 28050571, 2016). "A positive correlation was found between the severity of liver disease and level of IL-22 in cirrhotic patients or hepatitis B virus (HBV) patients." (PMID 28050571, 2016). "Presently, increasing evidence in animal models and humans have demonstrated the importance of IL-22 in the initiation and maintenance of liver disease." (PMID 24623532, 2014). "This review concisely summarizes the role of IL-22 in the development progression of liver disease of different etiologies." (PMID 24623532, 2014). "A PubMed and Web of Science databases search was performed for studies providing evidences on the role of IL-22 in liver diseases." (PMID 24623532, 2014). "In this review, we summarize our current understanding of the involvement of IL-22 in different development and pathogenesis pathways of liver diseases, as well as its clinical implications and therapeutic potential." (PMID 24623532, 2014). "On the whole, with the exception of experimental hepatitis B virus infection, murine models largely suggest a tissue protective function of IL-22 in hepatic disorders." (PMID 22967278, 2012).
liver disease (continued). "The tissue protective properties of IL-22 also extend to experimental ventilator-induced lung injury and, in particular, to specific models of hepatic diseases." (PMID 22967278, 2012). "The potential role of IL-22 in liver diseases has been intensively studied in murine models for T cell-mediated hepatitis, fulminant hepatic failure, alcoholic liver injury and regeneration after hepatectomy." (PMID 22967278, 2012). "The pathophysiological relevance and prognostic potential of serum IL-22 in patients with liver diseases of various etiologies is less clear." (PMID 22967278, 2012). "The potential of IL-22 as a parameter of liver diseases is further highlighted by detection of its increased expression in patients' liver biopsy specimens." (PMID 22967278, 2012). "Here we comprehensively analyzed systemic IL-22 concentrations in a cohort of 120 patients suffering from severe liver cirrhosis and thoroughly related those data to the survival of liver disease." (PMID 22967278, 2012). "Follow-up analyses of serum IL-22 levels in patients with liver cirrhosis suggest that mean IL-22 levels increase during the course of liver disease." (PMID 22967278, 2012). "IL-22 is an emerging target for liver disease treatment that can promote hepatocyte regeneration." (PMID 41320154, 2025). "In summary, IL-17A and IL-22 are particularly significant among type 3 cytokines due to the wide investigation of their roles in the initiation, progression, and resolution of liver disease, notably MASLD, and their therapeutic potential and will thus be the focus of this review." (PMID 39156888, 2024). "It is known that IL-22 has a pro-inflammatory effect in the presence of IL-17 and can be regulated by IL-17, the increase of Th17 cells in HBV-infected hepatocytes, produces more IL-22, forming a positive feedback loop, which promotes fibrosis and liver disease." (PMID 39608222, 2024). "We demonstrated that delivery of interleukin-22 following phage-mediated lysis decreases indicators of liver disease in a model of alcohol binge-fed mice, while phage-mediated release of interleukin-22 or interferon-β increased the survival of mice exposed to body irradiation (36, –, 39)." (PMID 39480094, 2024). "IL-22, a member of the IL-10 cytokine family, acts as a hepatocyte survival factor and binds to receptors IL-22R1 and IL-10R2 to play a protective role in a variety of liver diseases, such as hepatitis, HF, and hepatocellular carcinoma." (PMID 37420298, 2023). "There is also a line of thought in the literature that IL-22 is detrimental in liver disease." (PMID 38162671, 2023). "The protective role of IL-22 in liver injury and hepatitis disease has been widely studied." (PMID 35592531, 2022). "The liver protection or liver damage shown by IL-22 in different liver diseases may be due to the stage dependence (i.e., acute and chronic) and/or disease dependence of IL-22." (PMID 36117587, 2022). "Likewise, IL-22 can be influenced due to a modulation of the intestinal microbiome by these liver diseases." (PMID 33851257, 2021). "Furthermore, this implies that many liver diseases exert not only direct effects on the levels of IL-22 in liver tissues but also imply indirect effects on IL-22 production by influencing the host microbiome." (PMID 33851257, 2021). "Targeting IL-22 is particularly promising as an alternative strategy to directly break the cycle of inflammatory cytokine and chemokine signaling, and the fusion protein using the IL-22 gene and nanocomplex is considered a new strategy to improve liver disease." (PMID 33841164, 2021). "Similarly, the expression of IL-22 was significantly increased in patients with hepatitis B and the levels of IL-22 in serum or in the liver are closely related to the severity of liver disease in patients with Hepatitis B viral infection." (PMID 32760208, 2020). "IL-22 is expected to be a new attractive candidate for human liver diseases therapy." (PMID 32760208, 2020).